RNU6-331P (RNA, U6 small nuclear 331, pseudogene)
Gene: Small nuclear RNA gene on chromosome 22 (29,899,587 to 29,899,693, reverse strand). Ensembl gene ENSG00000207455.
Homologues: Orthologues: chimpanzee U6 (99% identical), macaque U6 (94% identical), rat U6 (85% identical). Paralogues in human: RNU6-1235P (95% identical), RNU6-498P (95% identical), U6 (95% identical), RNU6-25P (90% identical), RNU6-33P (90% identical), RNU6-38P (90% identical), RNU6-476P (90% identical), RNU6-1 (89% identical), RNU6-2 (89% identical), RNU6-20P (89% identical), RNU6-22P (89% identical), RNU6-3P (89% identical), and 1288 more.